PPARG (peroxisome proliferator activated receptor gamma)
Diseases named in the same sentence as PPARG in open-access papers (continued):
Sharing a sentence is not in itself a finding about the gene and the disease.
type 2 diabetes (continued). "Furthermore, our findings also indicated the beneficial effects of combined treatment of PPARγ agonists with metformin, which decreased systolic and diastolic blood pressure in patients with type 2 diabetes." (PMID 38627464, 2024). "Genetic variants associated with glycated hemoglobin (HbA1c), Type 2 Diabetes (T2D), and antidiabetic drug targets (KCNJ11, ABCC8, PPARG, INSR, GLP1R, SLC5A2, and DPP4) were sourced from genome-wide association studies in the UK Biobank and the DIAMANTE consortium." (PMID 39640975, 2024). "Thiazolidinediones, peroxisome proliferator-activated receptor-gamma (PPAR-γ) activator, are compounds that enhance insulin sensitivity, effectively reducing plasma glucose levels and improving the lipid profile of individuals with type 2 diabetes." (PMID 38671903, 2024). "In addition, Peroxisome proliferator-activated receptor gamma (PPARγ), which regulates transcription of ADIPOQ gene, is associated with increased adiponectin levels and a reduced risk of type 2 diabetes." (PMID 38674417, 2024). "Both ABA and PPARγ agonists have previously been reported to ameliorate memory performance in Alzheimer’s disease and dietary ABA has been shown to upregulate PPARγ in immune cells and thereby reduce the severity of inflammatory bowel disease and type 2 diabetes in mice." (PMID 39742273, 2024). "Peroxisome proliferator-activated receptor γ (PPARγ), a target of thiazolidinediones used to treat patients with type 2 diabetes mellitus (T2DM), plays a crucial role in enhancing insulin sensitivity, promoting adipogenesis and exerting anti-inflammatory effects." (PMID 39431155, 2024). "Agonists of PPARγ, such as thiazolidinediones (e.g., pioglitazone, rosiglitazone), enhance insulin sensitivity and regulate glucose metabolism, making them effective treatments for type 2 diabetes." (PMID 39458951, 2024). "In general, the use of PPARγ agonists over type 2 diabetes was one of the earliest applications built upon the discovery and knowledge of PPARγ with clinical evidence as an antidiabetic agent, with approved experimental agonists including pioglitazone, rosiglitazone, and rivoglitazone." (PMID 39768147, 2024). "Thiazolidinediones such as rosiglitazone and pioglitazone, which are usually used in the treatment of type 2 diabetes, act as PPARγ agonists and stimulate the genes regulating insulin and fatty acid transcription, and restore the glycaemic profile in db/db mice." (PMID 37111244, 2023). "PPARγ represents a key target for the treatment of type 2 diabetes and metabolic syndrome." (PMID 37189440, 2023). "The identification of potent natural compounds with high binding affinity and stability for PPARγ couldlead to potential new therapies for diseases such as type-2 diabetes and metabolic syndrome." (PMID 37901293, 2023). "Therefore, our results suggest that selective modulation of PPARγ S273 phosphorylation by ligands should be achieved in the development of new therapies for type 2 diabetes treatment, while considering the potential effects on the liver." (PMID 37189379, 2023). "Activation of PPARγ has been shown toenhance insulin sensitivity, promote glucose uptake in adipose tissue and skeletal muscle, and reduce inflammation, which are criticalfactors in the pathogenesis of type 2 diabetes and metabolic syndrome." (PMID 37901293, 2023). "In co-localisation analysis, however, there was little evidence of shared causal variants for type 2 diabetes liability and cancer endpoints in the PPARG locus, although these analyses were likely underpowered." (PMID 37171501, 2023). "Pioglitazone (PZ) is a drug used to treat type 2 diabetes by enhancing insulin sensitivity, acting as an agonist of peroxisome proliferator-activated receptor gamma (PPAR-γ), a nuclear receptor that regulates glucose homeostasis, lipid metabolism, and inflammation." (PMID 36232486, 2022).
type 2 diabetes (continued). "Intriguingly, and of relevance to this work, the addition of PPARα agonistic activity to PPARγ, PPARγ, to PPARδ agonists has led to a higher safety profile, leading to their development for use in many diseases, including type 2 diabetes, dyslipidemia, and non-alcoholic fatty liver disease." (PMID 35288651, 2022). "Lupenone has been reported to play a role in type-2 diabetes by downregulation of PPARγ." (PMID 36557305, 2022). "In addition to their ability to target PPARγ for type 2 diabetes therapy, different TZD compounds are also in clinical trials for their tumor-suppressing effects." (PMID 36611922, 2022). "Such a PPARγ-regulating mechanism, ligand-dependent transrepression of transcription factors, has been described in the case of immune cells, and would open the door to the repurposing of type II diabetes mellitus drugs for their use in epilepsy." (PMID 35507634, 2022). "TZDs are PPARγ (PPAR-gamma) activators used for type-2 diabetes treatment." (PMID 35215339, 2022). "Moreover, it has been demonstrated that the type 2 diabetes drugs, Thiazolidinediones (TZDs), which are agonists for peroxisome proliferator-activated receptor-gamma (PPARγ) and block MPC activity, induce changes in fatty acid esterification." (PMID 34741717, 2022). "Though PPARγ agonist Rosiglitazone has been used for treatment of type 2 diabetes in clinic, whether the protective effects of PPARγ detected in the animal model could be extrapolated to the clinical application is subject to the future clinical trials." (PMID 33717177, 2021). "This review will focus on the clinical application of modulating PPARγ to treat type 2 diabetes." (PMID 34339734, 2021). "Several type 2 diabetes susceptibility genes are known to play a role in cancer development (e.g. TCF7L2, CDKN2A/B, AKT2, PPARG, PTEN and HNF1B) but the evidence is relatively scarce for shared genetic aetiology between type 2 diabetes predisposing alleles and the observationally associated cancers." (PMID 32705315, 2020). "Importantly, PPARγ agonist pioglitazone, a thiazolidinedione drug for type 2 diabetes, successfully restores IFN-γ production in tumor-infiltrating iNKT cells from both human patients and mouse models." (PMID 31974378, 2020). "Geniposide, an active component of Fructus Gardeniae, could enhance leptin signaling to attenuate the level of Aβ1–42 in Alzheimer's disease and activate PPARγ to reduce the blood glucose level in type 2 diabetes." (PMID 33178326, 2020). "PPARG is targeted by thiazolidinediones (TZDs), a class of agents used to treat type II diabetes." (PMID 32894083, 2020). "Consequently, potent full agonists of PPARγ, thiazolidinediones, have been widely used for the treatment of type 2 diabetes in clinical practice." (PMID 33260769, 2020). "Consequently, these side-effects resulted in a drastic reduction in the use of PPARγ agonists in the treatment of type 2 diabetes." (PMID 33776749, 2020). "PPARγ agonists, such as rosiglitazone and pioglitazone, are therapeutic agents for type 2 diabetes." (PMID 31766503, 2019). "PPARG was initially described as a TF involved in adipose tissue differentiation, and its synthetic agonists, including thiazolidinedione drugs, are used for the treatment of type II diabetes." (PMID 31319484, 2019). "NRs such as the GR (dexamethasone), RXR (bexarotene and alitretinoin), PPARα (fibrates), and PPARγ (thiazolidinediones) have already been successfully targeted by approved drugs for treating autoimmunity, cancer, hyperlipidemia, or type 2 diabetes, respectively." (PMID 31139192, 2019). "It demonstrates that TDQ treatment, associated with increased hepatic PPARγ and reduced DGAT2 expression, targets multiple risk factors of the type 2 diabetes; additionally, it is a glucose- and lipid-lowering agent with a strong ability to treat diabetic complications." (PMID 31019978, 2019).
type 2 diabetes (continued). "Interestingly peroxisome proliferator-activated receptor γ (PPARγ) agonist are insulin sensitizers and widely used in the treatment of type 2 diabetes and cardiac hypertrophy has been reported in few preclinical studies using such agonists." (PMID 31340810, 2019). "Among three subtypes of PPARs, PPARα and PPARγ have been widely applied in clinic because the related drugs are already available for treating metabolic disease including type II diabetes and dyslipidemia (such as PPARα agonist fibrates and PPARγ agonist thiazolidinediones)." (PMID 31073415, 2019). "Peroxisome proliferator-activated receptor gamma (Pparγ) signaling plays key roles in energy homeostasis, metabolic diseases and mediates the action of thiazolidinediones, potent insulin sensitizers and highly effective oral medications for type 2 diabetes." (PMID 29434026, 2018). "Uncovering how context‐specific differential regulation of distinct TZD responses is mediated by Cited4 may open up new possibilities for exploiting and personalizing PPARg modulation in type 2 diabetes or prediabetes." (PMID 29973382, 2018). "PF11 is also known as a novel partial peroxisome proliferator-activated receptor γ (PPARγ) agonist, which could be developed into a new PPARγ-targeted therapeutic drug against type 2 diabetes." (PMID 30323902, 2018). "PPARγ is an evolutionary conserved transcription factor belonging to the nuclear hormone receptor superfamily that plays important roles in adipogenesis and insulin sensitivity, type 2 diabetes, atherosclerosis, and cancer." (PMID 30563100, 2018). "Our study revealed unexpected sex‐, tissue‐, and context‐specific aspects of glitazone action which are relevant for the development and personalization of new therapeutic approaches targeting PPARg and adipose tissue metabolism in type 2 diabetes and prediabetes." (PMID 29973382, 2018). "It would be, therefore, important to measure how glycerol turnover and aquaporin expression are affected by both leptin and PPARγ expression in vWAT of obese and type-2 diabetics, in order to limit abnormal gluconeogenesis, either by impacting their vWAT, PPARγ, or hepatic PPARα signaling." (PMID 29914059, 2018). "Furthermore, we have attempted to delineate the structure of thiazolidinediones that is vital for the development of next generation PPARγ or PPARα/γ agonists to be used in the treatment of type 2 diabetes." (PMID 28656106, 2017). "A study in 2010 reported that Rg1 treatment could improve the expression of PPARγ and lipid metabolism in the treatment of Type 2 diabetes." (PMID 28656054, 2017). "RGZ is a synthetic PPARγ agonist, which has been used as an insulin sensitizer in Type 2 diabetes." (PMID 29201005, 2017). "PPARγ activation by glitazones enhances the breakdown of circulating triglycerides and also increases the concentrations of adiponectin, which are low in plasma of patients with type 2 diabetes mellitus." (PMID 28656106, 2017). "SR1664, a novel compound developed by the Scripps Institute in the United States and other institutions, is a PPARγ ligand that activates PPARγ to suppress PPARγ Ser273 phosphorylation, leading to enhanced insulin sensitivity, thereby playing a role in treating type 2 diabetes." (PMID 29230238, 2017). "Indeed, PPARγ has important roles in pathologies, such as obesity, cardiovascular diseases, type 2 diabetes, atherosclerosis, or lipodystrophy because it has lipophilic compounds as ligands: fatty acids and their derivatives, for instance." (PMID 29225614, 2017). "TZD, a synthetic ligand for PPARγ activation, is used in the treatment of type 2 diabetes." (PMID 28042289, 2016). "PPARγ agonists are currently in clinical use for the management of type 2 diabetes." (PMID 27352979, 2016).
type 2 diabetes (continued). "A total of eleven of genes were differently expressed in celiac patients compared with disease controls of which CD36, CD38, FOXP1, SELL, PPARA, PPARG, AGT previously associated with type 2 diabetes and AKAP6, NTNG1 with anorexia nervosa remained significant after correction for multiple testing." (PMID 27483138, 2016). "PPARγ is the target of TZDs that have been used extensively in patients with type 2 diabetes." (PMID 27430371, 2016). "In addition to its role in adipogenesis, the increased levels of PPARγ have been observed in inflammation, which is a typical condition of alcohol toxicity and type 2 diabetes." (PMID 27348013, 2016). "Pio-dependent glucose normalization did not require weight loss in the BBZDR/Wor type 2 diabetes rat model, suggesting that PPARγ regulates additional mechanisms besides adipose tissue and body weight." (PMID 26336514, 2015). "Pioglitazone (Pio) is a PPARγ agonist used for the treatment of type 2 diabetes." (PMID 26336514, 2015). "Although a few drugs that target PPARγ, such as troglitazone, rosiglitazone, and pioglitazone, have been approved for patients with type 2 diabetes, severe adverse effects have led to interest in the discovery of more diverse and novel compounds that target PPARα or PPARγ." (PMID 26225954, 2015). "Previous research showed that activation of PPARγ is mainly involved in regulating lipid metabolism, insulin sensitivity, and glucose homeostasis and its agonist has been used in the treatment of hyperlipidemia and type 2 diabetes." (PMID 25055851, 2014). "In conclusion, our study confirmed the almost zero occurrences of known rare PPARG SNPs and has shown that one of the common SNPs, His447His, may be protective against type 2 diabetes." (PMID 25197274, 2014). "The example of PPARγ in type 2 diabetes also illustrates that it may be worthwhile to gather additional evidence on all hits with a p-value < 0.05 (or even p < 0.1)." (PMID 25071867, 2014). "Based on an analysis of the evolutionary history of candidate genes, we showed that common 5′ variants in CDKAL1, CYB5R4, GAD2, and PPARG as well as an intronic type 2 diabetes-associated CDKAL1 variant exhibit non-neutral evolutionary patterns." (PMID 25222615, 2014). "PPARγ agonists are currently approved for use in humans for the treatment of type II diabetes, which may accelerate their path to clinical evaluation and impact." (PMID 24603727, 2014). "The PPARγ is a ligand-activated transcription factor involved in lipid metabolism and homeostasis that has been identified as the molecular target of insulin-sensitizing agents used to treat type 2 diabetes." (PMID 23674506, 2013). "The effects of tesaglitazar on augmenting insulin mediated control of hepatic and skeletal muscle glucose metabolism are consistent with the results of a number of studies with other PPARγ agonists on glucose metabolism in both animal models and even patients with type 2 diabetes." (PMID 24285952, 2013). "Since PPARγ is a key regulator of a number of pathways related to lipid and carbohydrate metabolism, this nuclear receptor represents an important pharmacological target for the treatment of diabetes type 2 and the metabolic syndrome." (PMID 23630612, 2013). "PPARG is of considerable importance due to its function as a nuclear hormone receptor with specific known interaction with sex hormones, for example with estrogen receptors, and due to its role in type 2 diabetes development and therapy." (PMID 23754948, 2013). "Particularly intriguing due to its relevance for type 2 diabetes and therapy is the PPARG, which showed association with WHR in women, but not in men." (PMID 23754948, 2013). "PPARγ agonists are currently in clinical use for the treatment of Type II diabetes." (PMID 23516550, 2013). "Additionally, Rg1 has been recently used to treat type 2 diabetes, as it can improve peroxisome proliferator-activated receptor γ (PPARγ) expression and lipid metabolism." (PMID 23520555, 2013).
type 2 diabetes (continued). "PPARγ has a central role in the regulation of glucose and lipid homeostasis and is involved in inflammatory processes and is an important drug target for treatment of Type 2 Diabetes and inflammation." (PMID 22363753, 2012). "The peroxisome proliferator-activated receptor-gamma has been the focus of intense research during the past decade because ligands for this receptor have emerged as potent insulin sensitizers used in the treatment of type II diabetes." (PMID 23213321, 2012). "In contrast, amelioration of insulin sensitivity by the PPARγ agonists, pioglitazone, and rosiglitazone, is accompanied by an increase in subcutaneous fat mass, but not in visceral fat weight in obese rats, and also in the patients with type 2 diabetes." (PMID 22253646, 2012). "Accordingly, we hypothesized that AT2 receptor stimulation by C21 might contribute to possible insulin-sensitizing/anti-diabetic effects in type 2 diabetes, with PPARγ activation." (PMID 23155382, 2012). "Our results suggest that SLC30A8 might therefore have a role in expansion of the β-cell and benefit from PPARγ agonists in the treatment of type 2 diabetes." (PMID 22208362, 2011). "Previous studies have described modulation of the PPARG Pro12Ala SNP by BMI in type 2 diabetes." (PMID 21663607, 2011). "One of the reasons why PPARs have been studied very intensively is that synthetic ligands of PPARα and PPARγ have been commonly used to treat metabolic diseases, such as dyslipidemia and type 2 diabetes, respectively, that affect millions of patients worldwide." (PMID 21382489, 2011). "Interestingly, the insulin-sensitizing PPARγ agonists used for treating type 2 diabetes, such as rosiglitazone and pioglitazone, have proven useful at ameliorating IBD effects in humans with UC." (PMID 21904603, 2011). "Our group has found that punicic acid ameliorates type 2 diabetes-induced inflammation by activating PPARγ and PPARα, and repressing TNF-α expression in white adipose tissue and liver and increases peripheral insulin sensitivity without causing any adverse side effects." (PMID 21904603, 2011). "Both PPARG and HNF1A are known susceptibility genes for type 2 diabetes." (PMID 22216000, 2011). "Several studies on the polymorphisms of PPARG such as Pro12Ala and His447His were previously performed in relation to inflammatory diseases such as IBD, type 2 diabetes and recently it has been suggested that PPARG polymorphisms were associated with the risk of asthma." (PMID 21044285, 2010). "Importantly, MDDC-mediated trans-infection is also inhibited by rosiglitazone, a PPARγ agonist that is currently licensed for the systemic treatment of type II diabetes." (PMID 20617179, 2010). "The best-characterized PPARγ agonists are thiazolidinediones (TZDs), including pioglitazone and rosiglitazone, which have insulin sensitizing activity and are currently used for the treatment of type 2 diabetes (Actos and Avandia, respectively)." (PMID 20339586, 2010). "In this context, PPARG should act as a negative control since it is thought to exert its influence on type 2 diabetes susceptibility through its action in other tissues (adipose tissue and liver) rather than the islet." (PMID 20548773, 2010). "Thus, synthetic PPARγ agonists, the thiazolidinediones (TZDs), are used in type 2 diabetes therapy as insulin sensitizers." (PMID 21057731, 2010). "The insulin sensitizing agent, rosiglitazone, is a PPARγ agonist used in the clinic to treat type II diabetes and recently has been reported to affect the phenotypic switch of macrophages from a pro to an anti-inflammatory profile as well as to affect macrophage infiltration into the EF pad." (PMID 20445733, 2010).